ANGPT1 (angiopoietin 1)
Diseases named in the same sentence as ANGPT1 in open-access papers (continued):
Sharing a sentence is not in itself a finding about the gene and the disease.
tumor (continued). "The tumor and intraglandular stromal cells in glandular PCa expresses both angiopoietin-1 and angiopoietin-2." (PMID 33841508, 2021). "Serum vascular endothelial growth factor (VEGF)-A, angiogenin, and angiopoietin-1 (Ang-1), which are secreted by tumors in the body and thus indicate total tumor growth and aggressiveness, are considered biomarkers for tumor angiogenesis." (PMID 33794813, 2021). "Serum biomarkers of tumor angiogenesis, including vascular endothelial growth factor-A (VEGF-A), angiogenin, and angiopoietin-1, were measured by enzyme-linked immunosorbent assays simultaneously." (PMID 33794813, 2021). "For example, VEGF and ANGPT1/2/4 produced by CAFs can significantly promote the angiogenesis of tumor cells." (PMID 33819917, 2021). "Further, several studies have reported an inhibiting effect of ANGPT1 on pathologic vascular expansion, suggesting its function as a tumour suppressor in several cancers, including CRC." (PMID 33573134, 2021). "The plasma angiopoietin-1 was downregulated from the median 971.3 pg/mL (interquartile range [IQR] 532.1–1569.3) to 417.9 (IQR 270.5–597.3) after tumor resection (p = 0.0020)." (PMID 32799882, 2020). "Platelets can mediate tumor cell growth, angiogenesis, and proliferation by releasing vascular endothelial growth factor, hepatocyte growth factor, basic fibroblast growth factor, and angiopoietin-1, as well as other angiogenesis and tumor growth factors." (PMID 33363021, 2020). "The abundance of TEMs, angiopoietin-1 and -2 were detected in tumor specimens of the HCC patients (n = 58), and together with the occurrence of histologic tumor necrosis, were associated with established clinicopathological characteristics and survival." (PMID 31830991, 2019). "Trebananib is a recombinant protein made by the fusion of a Fc and a peptide (peptibody) able to interact with angiopoietin 1 or 2 (Ang-1/2), impairing their binding toTIE-2 angiopoietin receptor, thus inhibiting tumor angiogenesis." (PMID 31370258, 2019). "A study showed that the activity of ANGPT1 induced the enlargement of tumor blood vessels to facilitate tumor cell dissemination and increased the ability of metastasis in tumors." (PMID 30540749, 2018). "Some studies suggested that the neutrophil levels were related to the systematic release of chemokines and ILs, including vascular endothelial growth factor, angiopoietin-1 and matrix metalloproteinases-9, which promoted tumor growth and metastasis in HCC." (PMID 28412745, 2017). "Neutrophils promote tumor growth and metastasis by secreting vascular endothelial growth factor, angiopoietin-1, and matrix metalloproteinase-9." (PMID 28894464, 2017). "Taken altogether, our findings reveal a novel role for miR-204/ANGPT1/TGFβR2 axis in tumor angiogenesis." (PMID 27703260, 2016). "In contrast, recombinant human angiopoietin-1 (RhAng1) 500 ng/mL treatment further suppressed tumor cell proliferation in endothelial niche." (PMID 27353038, 2016). "As was consistent with the qRT-PCR results, SPP1, COL1A1 and NT5E proteins were up-regulated, while the expression of HTRA1 and ANGPT1 were down-regulated in the tumor compared with ANPT groups (n = 29)." (PMID 27690016, 2016). "Meanwhile, the expression of ANGPT1 in tumor tissues and Ki67-positive proliferative cells was also evaluated by IHC staining using ANGPT1 or Ki67 antibody." (PMID 27240355, 2016). "We tested the effect of angiopoietin-1/Tie2 signaling modulation on tumor cell dormancy in BM endothelial niche." (PMID 27353038, 2016). "In the presented data, a low ANGPT1/ ANGPT2 expression ratio was observed especially on gene expression level in patients which were diagnosed with a larger tumour size." (PMID 26044849, 2015). "ANGPT2, in general, acts as ANGPT1-Tie antagonist and exerts anti-angiogenic effects in several tumour entities." (PMID 26044849, 2015).
tumor (continued). "Neutrophils have also been shown to promote tumor growth and metastasis by secreting vascular endothelial growth factor, angiopoietin-1, and matrix metalloproteinase-9." (PMID 25742141, 2015). "Tumor cell extravasation is regulated by many cytokines, including angiopoietin-1 (Ang1), a guardian of EC quiescence, as well as angiopoietin-2 (Ang2) and vascular endothelial growth factor (VEGF), the cooperative initiator and driver of angiogenesis." (PMID 25851538, 2015). "In contrast, PECAM1/CD31 and ANGPT1 were found downregulated in 80 % to 95 % of tumour samples with an average expression factor of 0.64 and 0.4, respectively." (PMID 26044849, 2015). "The specific overexpression of EFNB2 in small tumours with lymphatic spread and the typical decrease of the ANGPT1/ ANGPT2 ratio in larger tumours give weight to EFNB2 and angiopoietins as prognostic factors and potential therapeutic targets." (PMID 26044849, 2015). "In the case of GBM, it appears that tumor cell-derived angiopoietin-1 is an absolute requirement for normalization." (PMID 25506702, 2014). "The anti-angiogenic (CXCL9, CXCL10) and pro-angiogenic markers (VEGFa, CXCL2, CXCL5, Angiopoietin 1 and Angiopoietin 2) were quantified in the tumor by RTQPCR." (PMID 22815789, 2012). "The up-regulation of ANGPT1 has been investigated in many cancers, suggesting that ANGPT1 is strongly correlated with tumor malignancy." (PMID 22496856, 2012). "Number of peritoneal metastases (P<0.05), tumour volume, (P<0.05), vessel counts (P<0.01), and tumour cell proliferation (P<0.01) were significantly reduced in angiopoietin-1-expressing tumours." (PMID 12402160, 2002). "Second, due to the lack of an effect of PD-L1 blockade treatment on ANGPT1, the upregulation of ANGPT1 in combination with ICIs may enhance antitumor effects by facilitating tumor vascular normalization." (PMID 40370455, 2025). "Moreover, EGFR can modulate tumor angiogenesis by influencing the levels of factors such as angiopoietin-1 (Ang-1) and vascular endothelial growth factor (VEGF), consequently affecting the high invasiveness and metastatic potential of tumors." (PMID 40732366, 2025). "ANGPT1 is a significant regulator of epithelial cell proliferation; it is well recognized that epithelial carcinoma (EC) relies on cell proliferation and growth, which are essential processes for tumor formation." (PMID 40943497, 2025). "In tumour vessel xenografts, EPHB4 expression switches the vascularization program from sprouting angiogenesis to circumferential vessel growth, and reduces the permeability of the tumour vascular system via the activation of the angiopoietin-1/Tie2 system at the endothelium/pericyte interface." (PMID 38203852, 2024). "Additionally, it plays a significant role in tumor progression and chemotherapy resistance by regulating a variety of angiogenic factors, including angiopoietin 1 and angiopoietin 2, matrix metalloproteinase, and erythropoietin, along with energy pathways." (PMID 38542288, 2024). "Moreover, it has been demonstrated in vitro that the endothelial CD34 + progenitor cells migrate to PC sites in response to high levels of pro-angiogenic factors such as VEGF and Angiopoietin-1, secreted by tumor cells." (PMID 39020414, 2024). "The suitability of the DCE-MRI approach with albumin-binding gadofosveset to evaluate both tumor perfusion and vessel permeability was indicated by reduced perfusion and permeability parameters after angiopoietin-1 treatment, which is known for its vessel-stabilizing effects." (PMID 37221619, 2023). "In addition, it has been related to the modulation of proangiogenic factors such as vascular endothelial growth factor, angiopoietin-1, or interleukin-8, it influences inflammatory response and affects tumor suppressors." (PMID 37016307, 2023).
tumor (continued). "Grange and colleagues performed molecular characterization of microvesicles and identified specific mRNAs associated with tumor progression and metastasis, including VEGF, fibroblast growth factor-2 (FGF2), angiopoietin-1 (ANGPT1), ephrin-A3 (EFNA3), metalloproteinase (MMP)-2, and MMP9." (PMID 37762660, 2023). "Furthermore, VEGF was expressed in tumor cells, whereas angiopoietin-1 and -2, which promote vascular stability and functionality, were expressed in infiltrating host stromal cells." (PMID 34361027, 2021). "Interestingly, IFN-β itself was shown to possess anti-angiogenetic properties, and by upregulating angiopoietin 1 (Angpt1), suppressed abnormal angiogenesis and promoted tumor vascular maturation." (PMID 34830176, 2021). "To gain more insight into the mobilization of HPCs, we analyzed the expression of genes that regulate HPC maintenance and attraction in the bone marrow (CXCL12, c-kit ligand, angiopoietin-1, vascular cell adhesion molecule-1 and osteopontin) in tumor-bearing mice." (PMID 33603745, 2020). "This hypothesis was further confirmed by the significant increase of angiopoietin 1 and Pecam1 mRNA expression and by histological analysis of Pecam1 staining in apelin‐infused tumours." (PMID 32681609, 2020). "Besides, an experimental study demonstrated the distinct expressions of angiopoietin-1 and angiopoietin-2 in tumor samples of human oral SCC." (PMID 32799882, 2020). "Whether this finding could be due to a race-related difference in the tumor’s responsiveness to bevacizumab is deserving of further study to fully evaluate if ANGPT1, ANGPT2, TEK, FGF2, MMP9 and VEGFA are promising targets for future research." (PMID 28045923, 2017). "In addition, neutrophils promote tumor angiogenesis through the release of angiogenic factors, such as vascular endothelial growth factor, angiopoietin-1, and fibroblast growth factor-2." (PMID 28321405, 2017). "ANGPT1 also plays an important role in maintaining and stabilizing the tumor vasculature." (PMID 27292155, 2016). "We selected these genes because all six were present in the angiogenesis signature unique to PDAC, because CYP1B1 was the most significantly and highly up-regulated, and because ANGPT1, its receptors TIE1 and TEK, and HIF1A are commonly associated with pathways that enhance tumor angiogenesis." (PMID 26586478, 2016). "We selected five genes, SPP1, COL1A1, NT5E, HTRA1 and ANGPT1, of 15 genes whose coding proteins could be secreted from the pituitary, and we examined their tumor expression in 118 CD patients." (PMID 27690016, 2016). "In contrast, the expression of CD31 and ANGPT1 was downregulated in 80 % to 95 % of tumour samples." (PMID 26044849, 2015). "Thus, ANGPT1 that exerts its effect via Tie-2 signalling seems to play a lower-ranking role as an angiogenic factor in the neo-vascularisation of this tumour entity." (PMID 26044849, 2015). "However, when the delayed treatment group is followed for 28 days, the tumor seems to acquire resistance to treatment, leading to tumor growth and increased expression of factors such as angiogenin, angiostatin, angiopoietin-1/2, EGF-R and IGF-1." (PMID 25549350, 2014). "The most significant up-regulated genes identified in this tumor model are related to chromosome-end replication (Tert), invasion and metastasis (Plau, Serpine1, Mmp9 and Mmp1), cell adhesion (Itgb3 and Itgav) and angiogenesis (Angpt1 and Vegfa)." (PMID 24928374, 2014). "Blockade of angiopoietin-1 action by its antagonist angiopoitein-2 also may contribute to tumor vessel regression." (PMID 25549350, 2014). "These paradoxical findings suggest the effects of ANGPT1 on tumor characteristics and prognosis might be cancer-specific and also dependent on other angiogenesis-related genes." (PMID 22496856, 2012). "In the current study, we investigated whether the Angiopoietin 1 (Ang1)/Tie2 axis regulates the crosstalk between glioma cells and the tumor microenvironment." (PMID 21321379, 2010).
tumor (continued). "Among these, only angiopoietin-1 was appreciably up-regulated during tumor progression." (PMID 18232728, 2008). "In addition, angiopoietin-1 stimulated an infiltration of mesenchymal cells into the tumours, such that the coverage of microvessels by pericytes increased markedly, and the cancer cells were separated into small masses by the host stroma." (PMID 11870550, 2002). "However, angiopoietin-1 expression in tumours appears to be uncommon, and angiopoietin-1 overexpression in cancer cells has been reported to lead to inhibition of xenograft tumour growth." (PMID 11870550, 2002). "The effects of angiopoietin-1 on tumour growth and angiogenesis are controversial." (PMID 12402160, 2002). "We hypothesised that angiopoietin-1 would decrease tumour growth and ascites formation in peritoneal carcinomatosis." (PMID 12402160, 2002). "Importantly, provision of Angiopoietin-1 partially restores the angiogenic defects exhibited by the COUP-TFII–deficient mice, which supports the notion that COUP-TFII controls Angiopoietin-1/Tie2 signaling to regulate tumor angiogenesis." (PMID 28859090, 2017). "Thus, a possible signal transduction pathway, ANGPT1/TIE2 could participate in MCT-stimulated tumor angiogenesis." (PMID 27240355, 2016). "Moreover, the HMGIY/ANGPT1 signaling pathway plays an important role in tumor angiogenesis." (PMID 27292155, 2016). "Furthermore, the up-regulated expression of ANGPT1 in many tumors promotes tumor growth." (PMID 27292155, 2016). "Blockade of the stabilizing action of angiopoietin-1 may contribute to tumor vessel regression." (PMID 25549350, 2014). "However, several studies have reported an inhibiting effect of ANGPT1 on the pathologic vascular expansion, indicating that ANGPT1 may also function as a tumor suppressor in several cancers, including CRC." (PMID 22496856, 2012). "When tumor vasculature is normalized, there is pruning of superfluous 'immature' vessel sprouts, modulation of the pathologically thick basement membrane via activation of matrix metalloproteinases, and increased pericyte coverage mediated by the upregulation of angiopoietin-1." (PMID 21159176, 2010). "Through the HIF-1 pathway, they can secrete PDGF-β, VEGF, angiopoietin-1 (ANG-1), and MCP-1, thereby impairing the function of CD8+ T cells and dampening their anti-tumor effects, ultimately promoting tumor growth and metastasis." (PMID 39108760, 2024). "Both expression of ANGPT1 and ANGPT2 were intensely present in vascular endothelial cells especially in larger sized tumor vessels (≥ 15 μm) and some small vessels (< 15 μm)." (PMID 38619734, 2024). "The proangiogenic factors released by activated platelets, including VEGF and angiopoietin-1, facilitate neovascularization, lymphangiogenesis, and remodeling of the ECM, required for tumor growth and metastasis." (PMID 36831623, 2023). "ITGA5 and VEGFA were coexpressed in clusters 1 and 3, while ANGPT1 and ANGPT2 were minimally expressed in all tumor cells." (PMID 36999964, 2023). "Angiopoietins, including ANGPT1, ANGPT2, and ANGPT4, have been reported to act as ligands of the tyrosine kinase receptors TIE1 and TIE2 to activate MAPK signaling pathways during tumor angiogenesis in mammals." (PMID 37155312, 2023). "The secretion of VEGFs, angiopoietin-1/2, PDGF and TGF-β from tumor cells or other cell types robustly modulate the TME, which is a critical component of tumor biology." (PMID 37261338, 2023). "In tumor cells with ITGA5 knockdown, qRT‐PCR and Western Blotting revealed decreased expression of ANGPT1, ANGPT2, and VEGFA, when compared to control cells." (PMID 36999964, 2023). "Another crucial phenotype of cancer progression is angiogenesis triggered by tumor-related signals, such as vascular endothelial growth factor (VEGF) and angiopoietin-1 and -2 (Ang1, Ang2)." (PMID 36077619, 2022).
tumor (continued). "The activation of HIF1 can affect the expression of hundreds of genes, including vascular endothelial growth factor (VEGF) and angiopoietin-1 (ANGPT1), which can promote tumor survival." (PMID 35198442, 2022). "Rapid cell growth and disruption of the extracellular matrix are addressed by tumor cells with pro-vascularization signaling through VEGF, angiopoietin-1, and platelet-derived growth factor (PDGF), so that they can address their oxygen needs." (PMID 36364774, 2022). "Activation of HIF1 can affect the expression of hundreds of genes, including vascular endothelial growth factor (VEGF) and angiopoietin-1 (ANGPT1), which promote tumor survival." (PMID 36713375, 2022). "Corresponding to results here and elsewhere, DS patients have been found to have elevated levels of ANGPT1 and ANGPT2, which are protective against tumor metastasis, providing insight into the less solid tumors in DS." (PMID 35947952, 2022). "As a hypervascular tumor, HCC tends to induce the secretion of proangiogenic factors such as VEGF, angiopoietin-1 (ANGPT1), platelet-derived growth factor (PDGF), and basic fibroblast growth factor (bFGF)." (PMID 36300115, 2022). "These cells hold significant influence over tumor ECs through the wide range of secretory factors including IL-1β, VEGF, FGF2, TGFα, hepatocyte growth factor (HGF), and angiopoietin 1 (ANG1)." (PMID 34987525, 2021). "Angiopoietin-1/TEK signaling is important for vascular integrity, TEK knockout results in a significant increase in metastatic tumor cells in the lung." (PMID 33602230, 2021). "Angiopoietin-1 (ANGPT1), a secreted glycoprotein, is a physiological angiogenesis promoter during embryonic development and has an enigmatic role in tumor angiogenesis." (PMID 34039311, 2021). "Concerning the clinicopathological characteristics of LADC, PD-1 SNP, ANGPT1 SNP and HDAC9 SNP had been proven to influence the tumor progression significantly." (PMID 33799753, 2021). "Expression levels of ANGPT1 and ANGPT2, were measured in tumor TCM following treatment with 1,4-dihydroxy quininib alone or in combination with Bevacizumab or FOLFOX." (PMID 33008336, 2020). "Another study observed that the expression of angiopoietin-1 and angiopoietin-2 was upregulated in HCC patients and correlated with tumor dedifferentiation and tumor vascularity." (PMID 30959975, 2019). "Recently, the angiopoietin family of ligands, angiopoietin-1 and -2, has been demonstrated to selectively activate the endothelial cell membrane receptor tyrosine kinase TIE2 and to espouse tumor progression." (PMID 31830991, 2019). "Recent studies have indicated that neutrophil levels contribute to tumor growth and metastasis by the release of a number of chemokines, including vascular endothelial growth factor (VEGF), IL-8, angiopoietin-1, and matrix metalloproteinase-9." (PMID 31885890, 2019). "Conversely, platelets induce tumor angiogenesis by secreting proangiogenetic cytokines such as vascular endothelial growth factor (VEGF) and angiopoietin-1." (PMID 31662975, 2019). "Growth of tumor vessels depends not only on VEGF but also on various types of other angiogenic factors such as FGF-2 and angiopoietin-1." (PMID 30279483, 2018). "Lymphangiogenic growth factors, such as the VEGF family, angiopoietin-1, PDGFs, FGF, and other factors, promote metastasis of tumor cells to lymph nodes." (PMID 29976150, 2018). "The mRNA expression levels of VEGF, PDGF, angiopoietin-1 (ANGPT1) and TIE2 in tumor tissues were analyzed by qPCR." (PMID 27240355, 2016). "Angiopoietin-2 (Ang-2), a cytokine upregulated in tumor endothelial cells and some tumor cells including NSCLC, is a partial agonist and antagonist of angiopoietin-1 (Ang-1)." (PMID 27589869, 2016). "Although many genes were downregulated in GB-1 3D culture relative to the parental tumor (e.g. FGFR3, TGFβ1 and TYMP), certain genes were now upregulated (e.g. FGF2, ANGPT1 and EFNA3)." (PMID 26203665, 2015).